TRIM56 (tripartite motif containing 56)
Diseases named in the same sentence as TRIM56 in open-access papers (continued):
Sharing a sentence is not in itself a finding about the gene and the disease.
infection (16 papers, 2017 to 2025). The state of being infected such as from the introduction of a foreign agent such as serum, vaccine, antigenic substance or organism. "Infection with the Alpha variant was associated with a reduction in TRIM56 mRNA expression (median: -0.15) (p < 0.0001) versus the Omicron BA.5 variant." (PMID 38051999, 2023). "Infection with the Delta variant demonstrated lower levels of TRIM56 mRNA expression when compared with both the Alpha and Omicron BA.5 variants (p < 0.0001)." (PMID 38051999, 2023). "Mice deficient in TRIM56 exhibited increased susceptibility to lethal infection by herpes simplex virus type 1 (HSV-1)." (PMID 31067474, 2019). "In agreement with the in vivo data, bone marrow-derived macrophages (BMDMs) from Trim56-deficient mice are defective for IFN-α/β production following HSV-1 mutant γ34.5 virus (mutHSV-1) infection, in contrast to WT BMDMs that allow for significant type I IFN induction." (PMID 39861861, 2025). "Infection with HAdV-C5-GFP virus (HAdV-C5-GFP) further showed that TRIM56 overexpression increased both the number of infected cells and fluorescence intensity." (PMID 40459263, 2025). "Here, we report that TRIM56 is significantly upregulated during HAdV-C5 infection and plays a crucial role in promoting viral replication." (PMID 40459263, 2025). "Through its ubiquitinase activity and RNA binding ability, TRIM56 has been widely shown to directly target viral components to inhibit infection of several RNA viruses via its RING and C-terminal structural domains." (PMID 39747662, 2025). "Among these, TRIM56 overexpression had an intermediate effect, while knockdown of TRIM56 significantly reduced GFP-LC3 puncta formation during infection by mutHSV-1." (PMID 39861861, 2025). "Immunofluorescence assays revealed that E1A colocalized with TRIM56 in the cytoplasm during HAdV-C5 infection." (PMID 40459263, 2025). "Here, we report that TRIM56 is strongly upregulated during HAdV-C5 infection, with its expression correlating with increasing levels of the viral E1A protein, ultimately promoting HAdV-C5 replication." (PMID 40459263, 2025). "Very recently, the CVB3 virus has been suggested to induce TRIM56 cleavage in HeLa cells late post-infection." (PMID 39861861, 2025). "The present study aims to address the role played by a cellular protein termed TRIM56 in the infection of CVB3, a representative serotype of CVB, which is the causative agent of inflammatory heart disease." (PMID 39348396, 2024). "In view of this, we propose that TRIM56 gene can be a possible regulator of infection with SARS-CoV-2 by moderating the innate immune response and inhibiting the replication of SARS-CoV-2." (PMID 38051999, 2023). "In contrast, expression of TRIM56 was significantly stimulated by infection with both ncpBVDV strains (P < 0.01)." (PMID 33898551, 2021). "Trim6, Trim56, and Herc6 can also potentiate antiviral immunity by targeting other antiviral effectors in the infection of vesicular stomatitis virus (VSV), pestivirus, and influenza A virus, respectively." (PMID 31057555, 2019). "SK-N-SH cells were transduced with control vector (Bsr) or Flag-TRIM56, followed by infection by ZIKV." (PMID 31251739, 2019). "We also showed that WT and TRIM56−/− BMDMs showed similar levels of IFNα production upon infection with Sindbis virus or Parainfluenza virus." (PMID 29426904, 2018). "The K63-linked ubiquitination of STING mediated by TRIM56 and TRIM32 promotes TBK1–STING interaction upon infection with Sendai virus (SeV) or HSV-1." (PMID 29760876, 2018). "Infection of cycloheximide-treated cells induced robust SopA-driven degradation of TRIM56 and TRIM65." (PMID 28084320, 2017). "However, our study suggests that TRIM56 plays a distinct and previously uncharacterized role during HAdV-C5 infection." (PMID 40459263, 2025).
infection (continued). "Finally, we discovered that the viral protein US3 phosphorylates cytoplasmic HDAC6 to increase its deacetylase activity and interaction with TRIM56 in the early infection stage." (PMID 39747662, 2025). "For example, TRIM56-based interventions might offer new treatments for infections by influenza and coronaviruses, including COVID-19." (PMID 39861861, 2025). "Here, we also demonstrated that the depleting TRIM56 expression significantly reduced IFN-β mRNA expression during R. rickettsii infection, suggesting that TRIM56 might be a potential therapeutic target for infection with R. rickettsii." (PMID 38358243, 2024). "Additionally, we observed GFP+ NP cells in the IVDs injected with sh-TRIM56–carrying or sh-scrambled–carrying AAVs, demonstrating a high infection efficiency." (PMID 38488012, 2024). "To determine whether TRIM56 impacts ZIKV fitness, we conducted infection experiments in HeLa-FitA2-T56 cells with Tet-inducible expression of HA-tagged TRIM56 we developed previously." (PMID 31251739, 2019). "Finally, WT and TRIM56−/− BMDMs also showed similar viral RNA loads of ZIKV MR766 strain or H/PF2013 strain during 48 h infection periods." (PMID 29426904, 2018). "While wild-type L929 cells markedly induced ISRE-IFNβ promoter-luciferase expression upon HSV-1ΔICP34.5 infection, TRIM56(+) cGAS(−), TRIM56(−) cGAS(+), or TRIM56(−) cGAS(−) L929 cells showed defective ISRE-IFNβ promoter-luciferase expression under the same conditions." (PMID 29426904, 2018). "Furthermore, WT and TRIM56−/− BMDMs showed similar levels of IFNβ production upon infection of Flavivirus (Zika virus or Dengue virus), Sindbis virus, or Parainfluenza virus." (PMID 29426904, 2018). "In addition, time-course experiments showed that TRIM56−/− BMDCs weakly induced IFNβ production compared to WT BMDCs upon HSV-1ΔICP34.5 infection." (PMID 29426904, 2018). "In addition, endogenous TRIM56 interacted with viral E1A during HAdV-C5 infection." (PMID 40459263, 2025). "In addition, in overexpression settings, TRIM56 localizes in the cytoplasm, but a fraction of the protein enters the nucleus post-infection by influenza virus or hepatitis B virus (HBV), a process suggested to be critical for antiviral restriction of the two distinct viruses." (PMID 39861861, 2025). "Moreover, infection of cells with Salmonella expressing the binding-deficient SopA T338L mutant did not result in TRIM56 modification." (PMID 28084320, 2017). "The mRNA level of TRIM44 was upregulated upon infection with GDSH-01 and HEP-Flury strains, and the mRNA level of TRIM56 was elevated upon infection with GDSH-01 and HEP-Flury strains." (PMID 38731834, 2024). "We show that TRIM56 overexpression resulted in reduced virus yield and decreased levels of 3D and VP1 at 24 h of post-infection." (PMID 39348396, 2024). "Immunoblotting detection of ZIKV NS5 protein in input cell lysates confirmed the successful infection of ZIKV (lanes 6–9) and the antiviral effect imposed by WT TRIM56 (lane 7)." (PMID 31251739, 2019). "To pinpoint where TRIM56 exerts its antiviral action during ZIKV life cycle, we compared the kinetics of intracellular viral RNA accumulation at different times following infection between control and TRIM56-overexpressing cells." (PMID 31251739, 2019). "Upon infection by ZIKV, intracellular viral E and NS5 proteins accumulated to higher levels in TRIM56 knockdown SVGA cells than in cells bearing control shRNA (compare lanes 4 vs 3, and 6 vs 5)." (PMID 31251739, 2019). "We further demonstrate that SopA ubiquitinates TRIM56 and TRIM65, resulting in their proteasomal degradation during infection." (PMID 28084320, 2017). "In addition, we overexpressed TRIM56 in hTRIM56 deleted HMC3 cells and found that hTRIM56 promoted IFN-I production compared with mTRIM56 during infection with HSV-1 (Fig. EV5G)." (PMID 39747662, 2025).
infection (continued). "The tripartite motif-containing (TRIM) TRIM56 and TRIM65 host RING E3 ubiquitin ligases are normally involved recognizing foreign proteins and stimulating release of interferons to communicate to nearby cells to launch an immune response to combat infection." (PMID 33925937, 2021). "The IFNT induced expression of TRIM56, DDX58, and IFIH1 was further enhanced in the cells infected with KY (IFNT vs. IFNT+KY, P < 0.05–0.01) and that of TRIM56 and IFI27 was further increased in the presence of HO infection (IFNT vs. IFNT+HO, P < 0.05)." (PMID 33898551, 2021). "Time-course experiments also showed that TRIM56−/− BMDMs induced little or no IFNα/β production upon HSV-1ΔICP34.5 infection, whereas WT BMDMs robustly induced IFNα/β production." (PMID 29426904, 2018). "While WT BMDMs robustly induced IFNβ mRNA expression upon HSV-1 or HSV-1ΔICP34.5 infection, TRIM56−/− BMDMs displayed no increase of IFNβ mRNA expression under the same conditions." (PMID 29426904, 2018). "Infection of cells with complemented sopA deletion strains, expressing higher amounts of SopA relative to SL1344 WT Salmonella, resulted in increased modification of TRIM56." (PMID 28084320, 2017). "Moreover, both proteomics and biochemical data revealed that TRIM56 and TRIM65 are degraded in the course of infection and heterologous SopA expression with protein levels being restored by proteasome inhibition." (PMID 28084320, 2017). "Importantly, the interaction between HDAC6 and TRIM56 was significantly upregulated at 4 h p.i., suggesting that HSV-1 early infection promotes the nuclear-to-cytoplasmic transport of HDAC6 and enhances its interaction with TRIM56, thereby reducing TRIM56-mediated cGAS-STING activation." (PMID 39747662, 2025). "In addition, in agreement with our result, recent research that analyzed the transcriptional patterns of different cells using RNA-seq data after infection by a handful of viruses including IAV, SARS-CoV-2 and MERS-CoV showed a significant reduction in TRIM56 for IAV and SRAS-CoV-2 in A549 cells." (PMID 38051999, 2023). "By comparison, TRIM56 depletion had a marginal effect on autophagosome formation in the context of influenza A virus (IAV) infection and exhibited no impact following infection by a picornavirus, encephalomyocarditis virus (EMCV)." (PMID 39861861, 2025). "This antiviral barrier property, as shown in cell culture infection models, does not stem from general augmentation of IFN response, a conclusion also supported by the observations that TRIM56 does not restrict vesicular stomatitis virus (VSV, a Rhabdoviridae member) or HCV." (PMID 39861861, 2025). "Furthermore, TRIM56(+) cGAS(−), TRIM56(−) cGAS(+), and TRIM56(−) cGAS(−) cells failed to induce IP-10 mRNA expression upon HSV-1ΔICP34.5 infection, whereas wild-type (WT) L929 cells were capable of inducing IP-10 mRNA expression upon HSV-1ΔICP34.5 infection." (PMID 29426904, 2018).
tumor (15 papers, 2019 to 2025). "Clearly, compared with LGG, TRIM56 has a stronger association with tumor proliferation and invasion related pathways in GBM." (PMID 38348047, 2024). "Combined with TCGA and CGGA cohort, TRIM56 was most closely correlated with LAIR1, CD44, PDCD1LG2 and CD274, and oncoplots were used to display the tumor mutation gene microlandscape of TRIM56 high expression group and low expression group." (PMID 38348047, 2024). "TMB was higher in TRIM56 high expression group, and the tumor mutation microlandscape of TRIM56 high expression group and low expression group showed that EGFR and PTEN mutation proportion in high expression group was significantly higher than that in low expression group." (PMID 38348047, 2024). "Interestingly, we found that the “EPITHELIAL_MESENCHYMAL_TRANSITION” gene set, which is closely related to tumor invasion and proliferation, was more enriched in GBM than LGG, and TRIM56 was more strongly associated with tumor proliferation and invasion-related pathways in GBM." (PMID 38348047, 2024). "Clearly, the correlation between TRIM56 expression level and tumor purity in GBM was higher than that in LGG." (PMID 38348047, 2024). "We further calculated the correlation between tumor purity and TRIM56 expression by estimate algorithm." (PMID 38348047, 2024). "We constructed a multi-gene signature based on cell markers of tumor cells with high TRIM56 expression to enhance the prediction of cancer patient prognosis." (PMID 38348047, 2024). "In order to explore the expression of TRIM56 on a pan-cancer scale, we used TCGA database and GTEx database to analyze the expression level of TRIM56 in tumor tissues and normal tissues." (PMID 38348047, 2024). "We also calculated the correlation between TRIM56 expression level and tumor purity in LGG and GBM, respectively." (PMID 38348047, 2024). "Then TRIM56 overexpression cell lines were constructed for EdU assay, wound healing assay, flow cytometry and tumor xenograft model in vivo to validate the enrichment analysis results more specifically." (PMID 38348047, 2024). "Heatmap of GSVA scores of the autophagy and ubiquitin‐proteasome systems between TRIM56‐high and TRIM56‐low TCGA‐LIHC tumor samples." (PMID 38463397, 2024). "There was a significant positive correlation between TRIM56 and immune score, indicating that TRIM56 was mainly expressed in non-tumor cells, including stromal cells and immune cells." (PMID 38348047, 2024). "Reviewing the antiviral and tumor regulatory functions and specific mechanisms of TRIM56 is beneficial to provide new ideas for developing novel antiviral drugs and enriching therapeutic strategies against tumors." (PMID 36902478, 2023). "TRIM56 overexpression significantly enhanced the in vivo tumor development and shortened the survival period." (PMID 36870986, 2023). "Although some studies have reported on TRIM56 in tumors, the specific mechanism through which it influences tumor cell function remains elusive." (PMID 36870986, 2023). "A recent study also revealed a correlation between increased TRIM56 expression and reduced tumor radio-sensitization in GBM." (PMID 36870986, 2023). "In lung adenocarcinoma, hepatocellular carcinoma, and multiple myeloma, TRIM56 inhibits tumor progression by regulating the Wnt and TLR3/TRIF signaling pathways." (PMID 36870986, 2023). "Previous studies have elucidated that TRIM21, TRIM26, TRIM35, TRIM50, and TRIM56 acted as tumor suppressors by inhibiting tumor cell proliferation, and TRIM3, TRIM16, TRIM21, TRIM25, and TRIM26 negatively regulated migration and invasion in HCC cells." (PMID 35142083, 2022). "In both in vitro assays and in vivo xenograft models in mice demonstrated that TRIM56 depletion significantly suppressed tumor progression." (PMID 36471347, 2022). "In this ex vivo model, invasion of P3-sh-TRIM56 tumor spheroids into rat brain-like organoids was reduced relative to the control cell population." (PMID 36471347, 2022).
tumor (continued). "TRIM24 and TRIM56 were found to interact with ERα, stabilizing its chromatin interactions, thereby enhancing estradiol-stimulated tumor cell proliferation." (PMID 34208621, 2021). "In contrast, previous studies have identified TRIM56 as a tumor suppressor through activation of TLR3/TRIF signaling pathway, which was consistent with the result that TRIM56 expression was a favorable indicator of MIBC in this study." (PMID 31866765, 2019). "As a factor that promotes interferon production, we hypothesized that TRIM56 plays an important role in tumor immunity." (PMID 38348047, 2024). "We found that the expression of TRIM56 in C2 subgroup was significantly higher than that in other subgroups, which was defined as TRIM56 high expression tumor cell subgroup, and the remaining cell groups were defined as low expression tumor cell subgroup." (PMID 38348047, 2024). "Based on the clear correlation between TRIM56 and interferon production in previous studies, and the anti-tumor effect of interferon, we speculate that TRIM56 is a protective factor in most tumors." (PMID 38348047, 2024). "However, in breast cancer, TRIM56 promotes tumor progression by stabilizing ER alpha and is correlated with an unfavorable prognosis." (PMID 36870986, 2023). "This suggests that TRIM56 may play different pro- or anti-cancer functions in different tumor types." (PMID 36902478, 2023). "In recent years, many studies have revealed the function of TRIM56 in tumor development." (PMID 36902478, 2023). "Here, we show that in LUAD, tumor-derived exosomal circZNF451 may elicit ubiquitination of FXR1 via the E3 ligase TRIM56 in macrophages." (PMID 36209117, 2022). "Then, we further investigated the role of TRIM56 in tumor growth by xenograft mice models." (PMID 31000690, 2019). "Additionally, TRIM56 plays distinct roles in different tumor types." (PMID 36870986, 2023). "Thus, TRIM56 function may be dependent on the cellular environment, and thus requires further study in diverse tumor types to more fully understand the roles of TRIM56 in the development of cancer." (PMID 36471347, 2022). "The TRIM56-mediated degradation of DVL2 inactivates Wnt signaling and thus inhibits tumor development." (PMID 36902478, 2023). "Since TRIM3 has been shown to have a role as a tumor suppressor in GBM, we focused our investigation on the function of TRIM56 in the development of GBM." (PMID 36471347, 2022). "In fact, both TRIMs’ aberrant overexpression in BC is correlated with poor survival of BC patients, and depletion of these TRIMs leads to reduced cell proliferation, as has been shown for tumor-derived BC cells for TRIM24 and MCF7 cells for TRIM56." (PMID 34208621, 2021). "Because OC is primarily a tumor of epithelial origin, the expression of TRIM proteins was analyzed in epithelial cells, and the eight most highly expressed genes (TRIM28, TRIM27, TRIM33, TRIM38, TRIM47, TRIM56, TRIM8, and TRIM24) were determined." (PMID 38881325, 2024). "In recent years, its role in direct antiviral and tumor development has also attracted the interest of researchers, but there is no systematic review on TRIM56." (PMID 36902478, 2023). "The expression level of TRIM56 is not consistent among different tumor types, and its expression changes are closely related to tumor development and prognosis." (PMID 36902478, 2023). "TRIM56 expression levels are in this context not consistent across tumor types, which may indicate that TRIM56 exerts different cancer-promoting or cancer-suppressing functions in different tumor types." (PMID 36471347, 2022).